CD4 (CD4 molecule)
Diseases named in the same sentence as CD4 in open-access papers (continued):
Sharing a sentence is not in itself a finding about the gene and the disease.
bipolar disorder (11 papers, 2019 to 2025). A disorder of the brain that causes unusual shifts in mood, energy, activity levels and the ability to carry out day-to-day tasks. "This study used CellPrintTM enhanced flow cytometry to study 28 proteins representing a spectrum of cellular pathways in monocytes and CD4+ lymphocytes before and after lithium treatment in patients with bipolar disorder (BD)." (PMID 36676744, 2023). "Second, CD3, CD4, CD8, and Lp (a) levels were significantly associated with anhedonia in male participants with unipolar and bipolar depression." (PMID 38012724, 2023). "Furthermore, higher levels of CD3, CD4, and CD8 and lower levels of Lp (a) were significantly associated with greater anhedonia in male patients with unipolar and bipolar depression." (PMID 38012724, 2023). "Furthermore, the combination of CD3, CD4, CD8, and Lp (a) may be a promising biomarker associated with anhedonia in male patients with unipolar and bipolar depression." (PMID 38012724, 2023). "The demographic and clinical data, immune-inflammatory markers (CD3, CD4, and CD8), and lipoprotein profiles [TC, TG, LDL-C, HDL-C, lipoprotein(a) Lp (a)] of 227 patients with unipolar and bipolar depression were collected." (PMID 38012724, 2023). "Numerous studies, including meta-analyses, have reported increased peripheral and central immune-inflammatory markers, such as T lymphocytes (CD3, CD4, and CD8), C-reactive protein, and pro-inflammatory cytokines in unipolar and bipolar depression." (PMID 38012724, 2023). "Third, the combination of CD3, CD4, CD8, and Lp (a) had the strongest predictive value for distinguishing anhedonia in male participants with unipolar and bipolar depression." (PMID 38012724, 2023). "The multivariate binary logistic regression model showed that CD3, CD4, CD8, and Lp (a) were independent predictors of anhedonia in male patients with unipolar and bipolar depression." (PMID 38012724, 2023). "First, the anhedonia group only presented higher levels of CD3, CD4, and CD8 and lower levels of Lp (a) in male patients with unipolar and bipolar depression." (PMID 38012724, 2023). "In this study, we report that BDI patients have significantly higher percentages of total T, CD4+ T, and CD71+ B cells than healthy controls, which echoes previous findings that patients with bipolar disorder have greater numbers of activated T and B cells." (PMID 31767892, 2019). "Furthermore, changes in the proportions of CD4+, CD8+, and Th17 T-cell subtypes have been reported in diseases where lithium is used in treatment, such as bipolar disorder." (PMID 38700635, 2025). "The combination of CD3, CD4, CD8, and Lp (a) might be a possible biomarker for identifying anhedonia in male patients with unipolar and bipolar depression." (PMID 38012724, 2023). "Collectively, these findings suggest that CD3, CD4, CD8, and Lp (a) might be possible biomarkers of anhedonia in male patients with unipolar and bipolar depression." (PMID 38012724, 2023). "Notably, CD3, CD4, CD8, and Lp (a) had limited predictive value for anhedonia; however, the combination of CD3, CD4, CD8, and Lp (a) showed the strongest predictive value for distinguishing anhedonia in male patients with unipolar and bipolar depression." (PMID 38012724, 2023).
bronchiolitis (11 papers, 2013 to 2025). Inflammation of the bronchioles characterized by swelling of the bronchioles and mucus accumulation. "NLF from bronchiolitis children predominantly contained neutrophils, and also low frequency of monocytes and few CD4+ and CD8+ T cells." (PMID 36561744, 2022). "From all these data we conclude that in the NLF of bronchiolitis children there is an age-dependent variation in the lymphoid compartment, containing CD4+ and CD8+ T cells from neonatal life, and distinct B cell subsets in infants older than 2 mo of age." (PMID 36561744, 2022). "We aimed to evaluate the relationships between regulatory T cell (Treg) percentage and cytokine production of in vitro‐stimulated CD4+ T cells during acute bronchiolitis and the development of recurrent wheezing in the first 3 years of life." (PMID 31901157, 2020). "We found that the numbers of CD3+ and CD4+ T cells, as well as the concentrations of IgD+ B cells and IgG, were positively correlated with RS in bronchiolitis patients." (PMID 28257632, 2017). "We found fewer numbers of CD3+ T cells and CD8+ T cells (P < 0.001, P = 0.0014), but higher numbers of CD4+ T cells (P = 0.0003) in bronchiolitis patients compared to healthy control subjects." (PMID 28257632, 2017). "Mixed Th1/Th2-type immune responses (including eosinophils, neutrophils, and both IL-13- and IFN-γ-producing CD4+ T cells) are also a feature of vaccine-enhanced RSV disease in mice and of human bronchiolitis (44, –, 46), indicating that dysregulation is the hallmark of RSV disease." (PMID 23926350, 2013). "Whereas Nφs, inflammatory monocytes and CD4+ and CD8+ T cells were always present in bronchiolitis NLF, B cell recruitment was delayed, with overall evidence of an immature humoral response and with B cell subsets present in children older than 2 mo." (PMID 36561744, 2022). "As expected, we detected both CD4+ and CD8+ T cells in the bronchiolitis NLF, with overall more CD4+ than CD8+ cells (n = 33)." (PMID 36561744, 2022). "As STAT3 is an important mediator for CD4+ T cells, CD8+ T cells, and B cell activation and proliferation, this was investigated in the context of RSV-induced bronchiolitis." (PMID 35406717, 2022). "In contrast to some reports of RSV bronchiolitis in infants and formalin-inactivated RSV vaccine–enhanced disease, CD4+ T cells responding to RSV almost exclusively expressed type 1 cytokines." (PMID 31815739, 2020). "Infants with bronchiolitis had fewer numbers of CD3+ T cells and CD8+ T cells, more number of CD4+ T cells, and higher CD4+/CD8+ ratios in their blood when compared with healthy control subjects." (PMID 28257632, 2017). "However, significant decreases of CD3+, CD8+ T cells, as well as significant increases of CD4+ T cells and CD19+ B cells were found in the serum of bronchiolitis infants." (PMID 28257632, 2017).
central nervous system lymphoma (11 papers, 2007 to 2025). "The circulating CD4/CD8 ratio is an adverse prognostic factor in refractory/relapsed DLBCL–PCNSL (primary central nervous system lymphoma), mantle cell lymphoma, and Waldenstrom macroglobulinemia in the HIV-negative population." (PMID 35873145, 2022). "In cases of CNS lymphoma, the CD4 count is often lower than 50 as in the current case." (PMID 37964357, 2023). "The emergence of EBV-associated central nervous system lymphomas correlates with the HIV-1–induced loss of EBV-specific CD4+ T cells rather than overall CD4+ T-cell loss." (PMID 32576602, 2020). "AIDS-related primary central nervous system lymphoma (AR-PCNSL) is an AIDS-defining disease that usually occurs when the CD4 count is less than 50 cells/μl." (PMID 34666791, 2021). "In the case when immune suppression is apparent (CD4 <200 cells/mm3) AIDS-related tumours, central nervous system lymphoma and OIs are the most important aetiological factors." (PMID 28443591, 2017). "In AIDS patients, the incidences of DLBCL, HL, BL, primary central nervous system lymphoma (PCNSL), and primary effusion lymphoma (PEL) are increased because of the lack of T cell–mediated immune surveillance, which suggests that CD4+ T cells play central roles." (PMID 33732260, 2021). "Primary central nervous system lymphoma (PCNSL) exists as an HIV-associated malignancy, with its etiology driven primarily by Epstein-Barr virus (EBV) in the setting of absence of EBV-specific CD4+ T cell function, with CD4 counts averaging <50 cells/microliter." (PMID 40201892, 2025).
coccidiosis (11 papers, 2019 to 2025). A parasitic infection caused by Coccidia. "CD4+ cell activation induced by cecal coccidiosis was assessed through immunohistochemical (IHC) examination." (PMID 40230796, 2025). "It has been found that CD4+ T lymphocytes, after being stimulated by antigen, promote the activity of natural killer cells and enhance the cytotoxic effect of T cells and play an important role in fighting coccidiosis primary infection." (PMID 36112763, 2022). "Given the ability of indoles to regulate the T cell immune response and the importance of T cell immunity in coccidiosis, in the present study, we investigated whether dietary indoles might regulate CD4+ T cell immunity in chicken coccidiosis." (PMID 30972060, 2019). "CD4 T lymphocytes in murine coccidiosis may produce soluble cytokines such as IFN-γ and IL-10." (PMID 38751432, 2024). "Additionally, dietary 25OHD3 at 100 μg/kg increased CD4+CD25+ cells and deceased CD8+CD25+ cells in coccidiosis-infected broilers and turkeys." (PMID 36230268, 2022). "An increase in the level of CD4+ and CD8+ T lymphocytes was observed in chickens immunized with E. tenella 3-1E protein, which uncovered the involvement of these two T cell subpopulations in resisting coccidiosis." (PMID 35669766, 2022). "Furthermore, several reports have demonstrated a notable rise in the proportion of CD4+ and CD8+ T cells in chickens following infection by Eimeria species, providing evidence that these two T lymphocyte subsets participate in combating coccidiosis." (PMID 38093398, 2023).
dyslipidaemia (11 papers, 2011 to 2025). "After adjustment, baseline dyslipidaemia still independently associated with the occurrence of CD4/CD8 ratio normalization [OR, 0.23 (0.07–0.79)]." (PMID 26485149, 2015). "Severe immune suppression (low CD4 count) has been associated with dyslipidaemia in ART-naive HIV infected persons." (PMID 24606888, 2014). "Interestingly, our findings demonstrate a strong positive correlation between dyslipidaemia and CD4+T cell counts, aligning with previous research." (PMID 38666515, 2024). "However, in a cohort of persons doing well on highly active antiretroviral therapy (HAART) with a sufficiently improved mean CD4 count, there is little variability in CD4 count of the group and therefore a difference in dyslipidaemia cannot be attributed to differences in CD4 counts." (PMID 24606888, 2014). "Despite the ageing of the cohort, there have been positive changes in the proportion with dyslipidaemia and, in line with increased use of effective combination ART (cART), increases in the median CD4 count and decreases in the median HIV RNA level over time." (PMID 27036962, 2016).
erythroderma (11 papers, 2017 to 2025). "Advanced cutaneous manifestations, including tumoral lesions or erythroderma, along with significant lymph node involvement, LCT, or a shift in immunophenotype from CD4 + to CD8+, are indicative of an increased risk of progression to extracutaneous involvement." (PMID 40355202, 2025). "In addition to erythroderma, SS is characterized by circulating malignant T cells that mirror the skin infiltrate, as well as evidence of an increased blood tumor burden (B2 stage) with aberrant T‐cell phenotypes, such as CD4+/CD26− or CD4+/CD7− populations, identified by flow cytometry." (PMID 40847689, 2025). "When beginning treatment, p4510 exhibited whole-body erythroderma, with 93% of lymphocytes having a CD4+CD26− phenotype and a CD4:CD8 ratio of 64:1." (PMID 40723261, 2025). "SS is characterized by erythroderma and the presence of Sézary cells in the blood, which are immunophenotypically CD4+CD26- or CD4+CD7- T cells." (PMID 28977902, 2017). "Both cohorts of scurfy recipients were viable and appeared phenotypically healthy until the end of the observation period, apart from mild symptoms of delayed growth and exfoliative dermatitis in individual mice that received tTreg cell-depleted CD4+GFP– T cells (data not shown)." (PMID 38164128, 2023).
Ewing sarcoma (11 papers, 2005 to 2025). A small round cell tumor that lacks morphologic, immunohistochemical, and electron microscopic evidence of neuroectodermal differentiation. "The proportions of 8 immune cells in 85 Ewing sarcoma patients and 3 normal samples were presented by the bar plot, encompassing B cells, cancer-associated fibroblasts, CD4+ T cells, CD8+ T cells, endothelial cells, macrophages, NK cells, and uncharacterized cells." (PMID 36092920, 2022). "In Schober’s study, CD4+ T cells display cytotoxic activity against cognate Ewing sarcoma target cells, both in vitro and in vivo, even if less efficiently compared to their matched-CD8+ TCR-T counterparts." (PMID 38545119, 2024). "A high proportion of bone marrow T cells with regulatory phenotype (CD4+CD25hiFoxP3+) were also found in bone metastatic Ewing sarcoma patients." (PMID 34229299, 2021). "TIL isolated from Ewing's sarcomas, GCTs and bone metastases are characterized by almost same amount of CD4+ and CD8+ populations (around 50%)." (PMID 16188028, 2005). "TGFB1 expression is highest in NK cells, CD4+ T regulatory cells, CD8+ T cells, and CD14+CD16− monocytes isolated from human Ewing tumors." (PMID 40858520, 2025). "The following T-cell subsets were identified in the Ewing sarcoma TME: cytotoxic T cells (CD8+ T), γδ T cells, naïve T cells, Th cells (CD4+ T), and regulatory T cells (Treg)." (PMID 37823774, 2023). "They studied the nature of tumor–host immune interactions within the Ewing sarcoma microenvironment, analyzing the presence and spatial distribution of infiltrating CD8(+)(/)CD4+ T-lymphocytes in therapy-naive Ewing sarcoma." (PMID 26779435, 2015).
gastric tumor (11 papers, 2017 to 2024). "GO-Y022 treatment of gastric tumor cells co-cultured with human CD4+ T cells increased Treg generation, which was significantly decreased in the presence of 2DG." (PMID 36814928, 2023). "Next, we performed a co-culture experiment using gastric tumor cells and human naïve CD4+ T cells to examine the ability of Foxp3+ Tregs generation in the tumor microenvironment." (PMID 36814928, 2023). "In contrast to CD8+ T cells, whose fraction stayed nearly unchanged between tumor and normal samples, we observed an over fivefold increase in CD4+ T cells in the gastric tumor samples." (PMID 36550535, 2022). "Therefore, naïve CD4+ T cells co-cultured with GO-Y022 treated gastric tumor cells increased Treg generation." (PMID 36814928, 2023). "We observed these non‐Treg CD4+FOXP3+ T cells exist in the gastric tumor tissue (data not shown) and up‐regulation of IFN‐γ response genes in the High‐High tumors." (PMID 32377339, 2020).
Giardia infection (11 papers, 2013 to 2022). "Asking if the moderate difference in susceptibility to Giardia infection correlated with the activity of Th17 cells, we surveyed RORγt and IL-17A expression by CD4+ T cells in BALB/c and C57BL/6 mice at steady state and two weeks post G. muris infection." (PMID 31889073, 2019). "We showed that G. duodenalis infection induces IL-22 secretion in a CD4+ T cell-dependent manner in a mouse model of the human Giardia infection." (PMID 35250996, 2022). "Host immunological memory is suggested by the isolation of Giardia-reactive CD4+ T lymphocytes from the peripheral blood of human subjects known to have been infected with G. intestinalis during an outbreak of giardiasis 5 years previously." (PMID 25347704, 2014). "A recent report described long-term CD4+ T cell proliferative responses in patients 5 years after acute giardiasis, suggesting unresolved immune activation during the post-clearance phase." (PMID 23991642, 2013). "Notably, ezrin and villin were found to be differentially regulated by immune-mediated mechanisms following Giardia infection; while ezrin proteolysis required CD4+ T cells alone, the cleavage of villin required both CD4+ and CD8+ T cell responses." (PMID 35250996, 2022). "In addition, the role of mucosal and circulatory CD4+ T cells has been described as essential to collaborate with the activation of B cells and control murine giardiasis." (PMID 34778111, 2021). "Untreated Giardia-infection may regulate innate and adaptive immune responses mediated by Th17 CD4+T cells and induction of Th1, Th2 and Th17 cytokines, including IL-2, IL-5, IL-6, IL-8, IL-12, IL-13, IL-23, IFN-γ and TNF-α." (PMID 30412580, 2018). "In humans, the evidence for a role of CD4 T cells in giardiasis is not as clear, although several clinical studies suggest an association of decreased CD4 T cell numbers with increased Giardia prevalence and greater risk of symptomatic infection." (PMID 35468132, 2022). "Both CD4+ and CD8+ cells contribute to increased IELs during giardiasis." (PMID 33919165, 2021). "The adoptive transfer of CD8+ T cells, but not CD4+ T cells, from infected mice into naïve mice led to reduced disaccharidase enzymatic activity in recipients, suggesting that CD8+ T cells are crucial for the induction of BB abnormalities typically observed during Giardia infection." (PMID 35250996, 2022).
gingivitis (11 papers, 2014 to 2025). A disorder involving inflammation of the gums; may affect surrounding and supporting structures of the teeth. "The high TGF-β levels, accompanied by IL-6 in peripheral blood lymphocytes, activated Th17 cells and caused elevated percentage of CD4+ IL-17A+ Th17 cells in the peripheral blood of gingivitis patients, thereby secreting corresponding inflammatory factor IL-17A." (PMID 34234776, 2021). "In animal models, inhibition of STAT3 or RORγt in CD4+T cells resulted in the suppression of gingivitis and alveolar bone resorption." (PMID 40933993, 2025). "Bosco and Birman (2002) further grouped the CLWH based on their CD4+ T-cell counts and degree of suppression and found gingivitis only prevailed in children with moderate to severe suppression (below 999 cells/mm3)." (PMID 36232165, 2022). "There is correlation between low levels of CD4 + T cells and caries severity, gingivitis and xerostomia and hyposalivation." (PMID 36167498, 2022). "Flow cytometry revealed significantly higher percentage of CD4+IL-17A+ T cells in the gingivitis group, relative to healthy controls." (PMID 34234776, 2021). "Analysis of CD4+IL-17A+Th17/CD4+CD25+Foxp3+Treg cells revealed a higher ratio in the gingivitis group, relative to healthy controls." (PMID 34234776, 2021). "In fact, in gingivitis conditions, the CD3+CD4+/CD3+CD8+ ratio approximately accounted for 2:1, whereas gingival cells from PDT lesions revealed a 1:1 CD3+CD4+/CD3+CD8+ ratio." (PMID 36829785, 2023). "The percentages of CD4+IL17A+Th17 cells and IL-17 significantly increased in the peripheral blood in the gingivitis group." (PMID 34234776, 2021). "Taken together, a possible mechanism of gingivitis is that an increase in TGF-β content, coupled with IL-10 upregulation, in peripheral blood lymphocytes activated Treg cells, while transcription factor Foxp3 participated in a synergistic effect, thereby producing CD4+CD25+Foxp3+Treg cells." (PMID 34234776, 2021). "However the number of natural Tregs (CD4+ CD25+ Fox P3+) was not significantly elevated in the gingivitis group compared to the healthy group." (PMID 31183266, 2019). "However the number of natural Tregs (CD4+ CD25+ Fox P3+) was not significantly elevated in the gingivitis group compared to the healthy tissue group." (PMID 31183266, 2019).